ENSG00000238326
Synonyms: LOC124901197
Gene: Small nucleolar RNA gene on chromosome 5 (56,000,518 to 56,000,621, reverse strand). Ensembl gene ENSG00000238326.
Gene Ontology:
Biological process: RNA processing
Cellular component: nucleolus
Homologues: Paralogues in human: SNORD13 (85% identical), SNORD13P1 (84% identical), SNORD13P3 (84% identical), SNORD13D (83% identical), SNORD13E (82% identical).